LINC01524 (long independently transcribed non-coding RNA 1524)
Gene: Long non-coding RNA gene on chromosome 20 (52,192,159 to 52,699,472, forward strand). Ensembl gene ENSG00000234948.
Diseases named in the same sentence as LINC01524 in open-access papers:
LINC01524 is named in the same sentence as 4 diseases in open-access papers, as found by Europe PMC text mining. Sharing a sentence is not in itself a finding about the gene and the disease. The quoted sentences say what the papers report.
gastric cancer (1 paper, 2024). A primary or metastatic malignant neoplasm involving the stomach. "MIR31HG functions as an oncogenic gene in CRC, while LINC01524 is associated with overall survival in gastric cancer with Hp infection." (PMID 39639610, 2024).
cancer (1 paper, 2023). A tumor composed of atypical neoplastic, often pleomorphic cells that invade other tissues. "The Chr20:52317726–52320951 loci are located with the long intergenic non-protein coding RNA LINC01524, a prognostic biomarker and an enhanced factor of cancer." (PMID 36991510, 2023).
tumour (1 paper, 2024). "In comparison with peritumoral tissues (normal), MIR31HG showed elevated amounts in tumour tissues (tumour), while MIR9_3HG, LINC00334, MIR7_3HG, AC022915.2, AC048382.5, AC009315.1, AL079338.1, LINC01524, AC005520.2, AC245407.2, AC009690.2 and LINC01322 had lower levels." (PMID 39639610, 2024).
LINC01524 also shares sentences with these, for which no sentence is quoted: sexual dysfunction (1 paper).